TXK (TXK tyrosine kinase)
Description:
Non-receptor tyrosine kinase that plays a redundant role with ITK in regulation of the adaptive immune response. Regulates the development, function and differentiation of conventional T-cells and nonconventional NKT-cells. When antigen presenting cells (APC) activate T-cell receptor (TCR), a series of phosphorylation leads to the recruitment of TXK to the cell membrane, where it is phosphorylated at Tyr-420. Phosphorylation leads to TXK full activation. Also contributes to signaling from many receptors and participates in multiple downstream pathways, including regulation of the actin cytoskeleton. Like ITK, can phosphorylate PLCG1, leading to its localization in lipid rafts and activation, followed by subsequent cleavage of its substrates. In turn, the endoplasmic reticulum releases calcium in the cytoplasm and the nuclear activator of activated T-cells (NFAT) translocates into the nucleus to perform its transcriptional duty. Plays a role in the positive regulation of IFNG transcription in T-helper 1 cells as part of an IFNG promoter-binding complex with PARP1 and EEF1A1. Within the complex, phosphorylates both PARP1 and EEF1A1. Also phosphorylates key sites in LCP2 leading to the up-regulation of Th1 preferred cytokine IL-2. Phosphorylates 'Tyr-201' of CTLA4 which leads to the association of PI-3 kinase with the CTLA4 receptor.
Synonyms: PTK4; RLK; TKL; PSCTK5; BTKL
Tractability: Small molecule: an approved drug acts on it; a high-quality ligand is known; it belongs to a druggable protein family. Antibody: UniProt places it where antibodies can reach, with high confidence; its Gene Ontology location is reachable by antibodies, with high confidence; the Human Protein Atlas places it where antibodies can reach. PROTAC: a small molecule that binds it is known.
Target class: TK protein kinase group; Kinase; Protein Kinase; Enzyme; Tyrosine protein kinase Tec family
Gene: Protein-coding gene on chromosome 4 (48,063,158 to 48,134,250, reverse strand). Ensembl gene ENSG00000074966.
Subcellular location: Cytoplasm; Nucleus; Cell membrane
Subcellular location (Human Protein Atlas): Cytosol; Nucleoplasm; Nucleoli; Plasma membrane
Pathways (Reactome):
Immune System: FCERI mediated Ca+2 mobilization
Gene Ontology:
Molecular function: protein binding; protein tyrosine kinase activity; non-membrane spanning protein tyrosine kinase activity; ATP binding; protein kinase activity
Biological process: positive regulation of transcription by RNA polymerase II; positive regulation of type II interferon production; positive regulation of type II interferon-mediated signaling pathway; protein autophosphorylation; protein phosphorylation; regulation of gene expression; adaptive immune response; positive regulation of cytokine production; T cell receptor signaling pathway
Cellular component: cytoplasm; cytosol; nucleolus; nucleoplasm; nucleus; plasma membrane
Genetic constraint (gnomAD): Loss-of-function variants: 35 observed, 55.17 expected, observed/expected ratio (o/e) 0.63, 90% interval 0.48 to 0.84. The upper end of that interval is the gene's LOEUF score, 0.84, which puts it in group 3 of 6, group 1 being the genes least tolerant of losing a copy. Missense variants: 450 observed, 513.83 expected, observed/expected ratio (o/e) 0.88, 90% interval 0.81 to 0.95. Synonymous variants: 160 observed, 171.49 expected, observed/expected ratio (o/e) 0.93, 90% interval 0.82 to 1.06.
Homologues: Orthologues: chimpanzee TXK (99% identical), pig TXK (90% identical), rabbit TXK (88% identical), dog TXK (88% identical), mouse Txk (83% identical), rat Txk (80% identical), guinea pig TXK (77% identical). Paralogues in human: TEC (58% identical), ITK (54% identical), BTK (52% identical), BMX (46% identical), FYN (34% identical), FGR (34% identical), LYN (34% identical), SRC (34% identical), BLK (34% identical), ABL1 (33% identical), HCK (33% identical), YES1 (33% identical), and 20 more.
Diseases named in the same sentence as TXK in open-access papers:
TXK is named in the same sentence as 27 diseases in open-access papers, as found by Europe PMC text mining. Sharing a sentence is not in itself a finding about the gene and the disease. The quoted sentences say what the papers report.
hepatocellular carcinoma (13 papers, 2014 to 2025). A malignant tumor that arises from hepatocytes. "Four of them are TEC family kinase members: ITK, interleukin-2-inducible T-cell kinase; TEC, tyrosine kinase expressed in hepatocellular carcinoma; BMX, bone marrow-expressed kinase; and RLK/TXK, resting lymphocyte kinase/ T and X cell expressed kinase." (PMID 33777941, 2021).
lymphoma (3 papers, 2021 to 2024). A malignant (clonal) proliferation of B- lymphocytes or T- lymphocytes which involves the lymph nodes, bone marrow and/or extranodal sites. "Analytical results indicated that some inferred genes, such as RAC3, TEC, IRAK2/3/4, PRKCE, SMAD3, BLK, TXK, PRKCQ, were associated with the initiation and progression of lymphoma." (PMID 34899868, 2021). "Other inferred genes, such as BLK (ENSP00000259089), TXK (ENSP00000264316), and PRKCQ (ENSP00000263125), have also been associated with lymphoma." (PMID 34899868, 2021). "Similarly, MIATNB and TXK loci hypomethylated in normal T-cells gained methylation in all tested lymphomas." (PMID 38464090, 2024). "The analytical results showed that some of these genes (RAC3, TEC, IRAK2/3/4, PRKCE, SMAD3, BLK, TXK, PRKCQ) could be novel lymphoma-associated genes." (PMID 34899868, 2021).
Arterial thrombosis (1 paper, 2023). The formation of a blood clot inside an artery. "Of these, six genes were most strongly associated with both venous and arterial thrombosis: G0S2, BCL2A1, TNFAIP6 (upregulated), CLIC3, BACH2, and TXK (downregulated)." (PMID 37035297, 2023).
bipolar disorder (1 paper, 2016). A disorder of the brain that causes unusual shifts in mood, energy, activity levels and the ability to carry out day-to-day tasks. "Mutation of the TXK gene has been identified to be a segregating factor for a number of neurodevelopmental disorders, including ASD, bipolar disorder, and intellectual disabilities." (PMID 27842596, 2016).
breast carcinoma (1 paper, 2023). "Thus, the activity of TXK on breast cancer requires further investigation." (PMID 36672350, 2023).
colitis (1 paper, 2023). Inflammation of the colon. "The dual ITK/TXK inhibitor RN694 exhibited efficacious effects in animal models of immune diseases such as colitis and psoriasis." (PMID 36821545, 2023).
lung carcinoma (1 paper, 2020). "Of those identified target genes, we selected HSPA6, histidine‐rich glycoprotein (HRG), ubiquitin D, prostaglandin E synthase (PTGES), tyrosine kinase (TXK), and MMP2 and measured those gene expressions in eight lung cancer cells 48 h after treatment with acRoots at 10 mg/mL." (PMID 32508044, 2020).
Neonatal sepsis (1 paper, 2021). Systemic inflammatory response to infection in newborn babies. "Interestingly, we found that the promoters of genes involved in T-cell regulation (i.e., CD3D, CD3G, UBASH3A, SIT1, and TXK) were hypermethylated in neonatal sepsis compared to controls, thereby resulting in decreased expression." (PMID 33659006, 2021).
venous thromboembolism (1 paper, 2023). Occlusion of the lumen of a vein by a thrombus that has migrated from a distal site via the blood stream. "We chose to quantify ANXA3, TNFAIP6, TXK, BACH2, and SERPINB2 mRNA expression in t-PAPS based on the results of a meta-analysis using a bioinformatics panel to explore the differences and similarities between venous thromboembolism (VTE) and cardiovascular disease." (PMID 37035297, 2023).
Venous thrombosis (1 paper, 2023). Formation of a blood clot (thrombus) inside a vein, causing the obstruction of blood flow. "Recently, dysregulation of the ANXA3, TNFAIP6, TXK, BACH2, and SERPINB2 genes has been associated with both arterial and venous thrombosis in the general population." (PMID 37035297, 2023).
cancer (3 papers, 2022 to 2025). A tumor composed of atypical neoplastic, often pleomorphic cells that invade other tissues. "We also observed upregulation of AUTS2 and TXK in liver NK cells, both of which been associated with poor prognosis and malignant progression in multiple human cancers." (PMID 40443661, 2025). "The tyrosine kinase, TXK, a signalling molecule involved in T Helper 1 cytokine production, is a predicted inhibitor of proliferation in cancers such as breast and colon." (PMID 36233808, 2022). "The methylation levels of TXK were similarly high in benign and carcinoma." (PMID 37460953, 2023). "A representative carcinoma-related hypermethylated DMR was identified from the CpG shore location, consisting of nine CpG promotor-TSS regions of the TXK gene." (PMID 37460953, 2023).
tumor (3 papers, 2011 to 2023). "We sought to explore whether TXK affects the malignant activity of tumor cells to influence prognosis through cellular experiments." (PMID 37207222, 2023).
TXK also shares sentences with these, for which no sentence is quoted: infection (7 papers); viral infections (2); Behcet disease (1); cardiovascular disease (1); ear infection (1); immune diseases (1); intellectual disabilities (1); neurodevelopmental disorder (1); oligodendroglioma (1); pancreatic cancer (1); pancreatic tumors (1); preeclampsia (1); psoriasis (1); T-cell leukemia (1); thrombosis (1).